TRIM24 (tripartite motif containing 24)
Diseases named in the same sentence as TRIM24 in open-access papers (continued):
Sharing a sentence is not in itself a finding about the gene and the disease.
colorectal cancer (10 papers, 2020 to 2026). A primary or metastatic malignant neoplasm that affects the colon or rectum. "TRIM24 is upregulated in colorectal cancer and negatively correlates with patient survival, with higher TRIM24 expression associated with shorter survival times." (PMID 39160596, 2024). "Previous research found that upregulation of TRIM24 was significantly associated with poor survival of colorectal cancer patients." (PMID 32677374, 2020). "TRIM24 was amplified and upregulated in colorectal carcinoma, and TRIM24 levels were negatively associated with patient survival." (PMID 32677374, 2020). "The crucial role of TRIM24 in colorectal cancer cell proliferation is facilitated by the DANCR/KAT6A complex, which enhances TRIM24 association with H3K23ac and subsequently recruits YAP to chromatin, contributing to increased cell proliferation." (PMID 39160596, 2024). "Another research provided evidence that TRIM24 interaction with H3K23ac, mediated by the DANCR/KAT6A complex, enhances oncogenic processes associated with the YAP signaling pathway in colorectal cancer." (PMID 39160596, 2024). "TRIM24 significantly influences proliferation, migration, invasion, and stem-like characteristics in colorectal cancer cells." (PMID 39160596, 2024). "Trim24 has been identified as an oncogene in colorectal cancer using lentivirus-mediated RNA interference knockdown in HCT116 human colorectal cancer cells, which significantly decreased cell proliferation." (PMID 35801156, 2022). "In this study, we found that TRIM24 plays a critical role in the proliferation of colorectal cancer cells via YAP signaling." (PMID 32677374, 2020). "We evaluated the expression of TRIM24 in colorectal cancer patients, and found a positive correlation between the expression pattern of the protein and the clinical outcomes." (PMID 32677374, 2020). "We further found that the DANCR/KAT6A complex promoted the association of TRIM24 with H3K23ac, thereby inducing TRIM24‐mediated recruitment of YAP to the chromatin, and promoting proliferation of colorectal cancer cells." (PMID 32677374, 2020). "Another study reported that knockdown of TRIM24 significantly inhibited the growth of colorectal cancer cells, and induced apoptosis." (PMID 32677374, 2020). "TRIM24 was shown to be oncogenic in colorectal cancer, but the relationship between the DANCR/KAT6A complex and TRIM24 in colorectal cancer had not previously been investigated." (PMID 32677374, 2020). "We found that TRIM24 was upregulated in colorectal carcinoma, and demonstrated that its expression is inversely correlated with the survival of colorectal cancer patients." (PMID 32677374, 2020). "Accumulating evidence has shown that TRIM24 plays an important role in the development of colorectal cancer." (PMID 32677374, 2020). "In the current study, we found that TRIM24 promotes YAP signaling for driving cell proliferation in colorectal cancer." (PMID 32677374, 2020). "Our results revealed a novel mechanism involving TRIM24‐YAP signaling for the regulation of colorectal cancer." (PMID 32677374, 2020). "We found that the DANCR/KAT6A complex upregulated TRIM24, and promoted cell proliferation in colorectal cancer." (PMID 32677374, 2020). "To investigate the molecular function of TRIM24 in colorectal cancer, we first evaluated TRIM24 expression in a colonic epithelial cell line, NCM460, and four colorectal cancer cell lines: LOVO, SW620, HT29, and HCT116." (PMID 32677374, 2020). "Here, we evaluated TRIM24 expression in colorectal cancer, and revealed a positive correlation between TRIM24 expression level and survival prognosis." (PMID 32677374, 2020). "TRIM24 was significantly upregulated in colorectal carcinoma, and its expression was negatively correlated with the survival of patients." (PMID 32677374, 2020).
colorectal cancer (continued). "Studies using patient-derived colorectal cancer organoids to compare BRAF fusions with various fusion partners (TRIM24, AGAP3, and DLG1) have shown that the 5′ partner plays a role in signaling and localization that affects signaling pathways and gene expression." (PMID 35326655, 2022). "The expression levels of TRIM24 were higher in all colorectal cancer cells than in NCM460 cells." (PMID 32677374, 2020). "We elucidated a previously unknown molecular mechanism involving DANCR/KAT6A‐mediated association of TRIM24 with H3K23ac, which subsequently results in enhancement of the oncogenic processes associated with the YAP signaling pathway in colorectal cancer." (PMID 32677374, 2020). "We also identified TRIM24 as a potential therapeutic molecule for targeting colorectal cancer." (PMID 32677374, 2020). "Our results indicated that TRIM24 is critical for the development of colorectal cancer." (PMID 32677374, 2020). "TRIM24 is dysregulated in many cancers, including colorectal carcinoma." (PMID 32677374, 2020). "To gain insights into the precise role of the DANCR/KAT6A complex in mediating the function of TRIM24 in colorectal carcinoma, we inhibited the expression of DANCR or KAT6A in both SW620 and HT29 cells, and found that both mRNA and protein expression of YAP were inhibited." (PMID 32677374, 2020). "TRIM24 expression is an independent prognostic factor and may play an important role in colorectal carcinogenesis, serving as a potential prognostic marker for human colorectal cancer." (PMID 39160596, 2024). "Therefore, we concluded that TRIM24 is positively correlated with YAP in colorectal cancer." (PMID 32677374, 2020). "Thus, the DANCR/KAT6A complex upregulates TRIM24 in colorectal cancer." (PMID 32677374, 2020). "Hence, we conclude that TRIM24 is essential to the development of colorectal carcinoma." (PMID 32677374, 2020). "Circ_RNF13 contributes to the stabilization of TRIM24 by suppressing F-box and WD repeat domain containing 7 (FBXW7)-mediated TRIM24 degradation, thereby enhancing chemosensitivity in colorectal cancer." (PMID 39160596, 2024). "TRIM24 is initially activated by the DANCR/KAT6A complex, thereby binding with H3K23ac and subsequently inducing TRIM24‐mediated recruitment of YAP to the chromatin, which ultimately promotes the proliferation of colorectal cancer cells." (PMID 32677374, 2020). "To evaluate the clinical implications of our results, we measured the expression levels of TRIM24 and YAP in clinical colorectal cancer specimens." (PMID 32677374, 2020). "Our data also suggest that DANCR/KAT6A promotes the association between TRIM24 and H3K23ac, thereby enhancing the TRIM24‐mediated recruitment of YAP to the chromatin, resulting in the proliferation of colorectal cancer cells." (PMID 32677374, 2020). "To determine the effect of YAP on TRIM24‐mediated cell growth in colorectal cancer, we overexpressed YAP in TRIM24‐knockdown SW620 and HT29 cells." (PMID 32677374, 2020). "However, the function of TRIM24 in colorectal cancer remains unclear." (PMID 32677374, 2020).
non-small cell lung carcinoma (10 papers, 2012 to 2022). A group of at least three distinct histological types of lung cancer, including non-small cell squamous cell carcinoma, adenocarcinoma, and large cell carcinoma. "A similar result was observed in non-small cell lung cancer with immunohistochemistry, and down-regulation of TRIM24 in head and neck squamous cell carcinoma (HNSCC) cells (WSU-HN6 cells) did not result in high mRNA expression level of RARα." (PMID 27689360, 2016). "Moreover, overexpression of TRIM24 was correlated with pTNM stage and differentiation in non-small cell lung cancer." (PMID 24409330, 2014). "To determine whether TRIM24 contributes to the invasion of non-small cell lung cancer cells, we conducted matrigel invasion assays." (PMID 22666376, 2012).
leukemia (9 papers, 2011 to 2025). A malignant (clonal) hematologic disorder, involving hematopoietic stem cells and characterized by the presence of primitive or atypical myeloid or lymphoid cells in the bone marrow and the blood. "However, whether TRIM24 or MYD88 plays a role in BETi resistance in leukemia has not been well determined." (PMID 37036970, 2023).
melanoma (9 papers, 2015 to 2024). A malignant, usually aggressive tumor composed of atypical, neoplastic melanocytes. "We produced an animal model through the subcutaneous inoculation of B16 melanoma cells to study the in vivo antitumor immune function of Trim24 in macrophages." (PMID 31554795, 2019). "In particular, we computationally predicted and experimentally validated the gene TRIM24 as a putative novel amplified driver in a melanoma patient." (PMID 25572314, 2015). "Indeed, both the culture supernatant of B16 melanoma cells and the tumor signature Th2 cytokine IL-4 significantly inhibited Trim24 expression in both mouse and human macrophages." (PMID 31554795, 2019). "On the other hand, even though TRIM24-BRAF fusion gene was previously reported to be present in a subset of melanomas, TRIM24 on its own has not been characterized as a driver and was ranked 671 in the list of frequently mutated genes in the TCGA melanoma data set." (PMID 25572314, 2015). "TRIM24-BRAF and CUX1-BRAF fusions have previously been reported in melanoma." (PMID 33441414, 2021). "To identify whether TRIM24HIGH, TRIM33HIGH, or TRIM66HIGH melanoma phenotype reflected the one observed in TRIM28HIGH expressing melanomas, we searched for genes that correlate with the expression of TRIM24, TRIM33, TRIM66, and TRIM28 in SKCM TCGA data." (PMID 33076560, 2020). "Interestingly, the expression of other close-related TRIM family members’ (namely, TRIM24, TRIM33, and TRIM66) does not correlate with the survival of melanoma patients, suggesting that TRIM28 is specifically involved in melanoma progression." (PMID 33076560, 2020).
ovarian carcinoma (9 papers, 2017 to 2025). A malignant neoplasm originating from the surface ovarian epithelium. "Data from Oncomine and immunohistochemistry of tissue samples demonstrated that TRIM24 expression was obviously elevated in ovarian carcinoma compared with normal ovary tissues." (PMID 35105347, 2022). "Moreover, TRIM24 negatively regulates the activity of FOXM1 to promote ovarian cancer progression." (PMID 37953273, 2023). "Moreover, high expression of TRIM24 predicted worse prognosis in ovarian cancer patients." (PMID 37953273, 2023). "However, the expression of TRIM24 in epithelial ovarian cancer (EOC) and its relationship with prognosis remain unclear." (PMID 35105347, 2022). "At the same time, a significant increase in the expression level of TRIM24 was also observed in non-small cell lung cancer (NSCLC), neuroblastoma and ovarian cancer." (PMID 39160596, 2024). "TRIM24 may be used as a new prognostic marker for EOC and may provide a new strategy for targeted therapy of epithelial ovarian cancer." (PMID 35105347, 2022).
papillary thyroid carcinoma (8 papers, 2012 to 2025). "Genomic profiling of the papillary thyroid carcinoma identified a TRIM24::BRAF fusion with a read count of 2221." (PMID 40362680, 2025). "In our case, the genomic profiling of papillary thyroid carcinoma led us to identify a TRIM24::BRAF fusion." (PMID 40362680, 2025). "Trim24 is a target gene that can generate chromosomal ectopic sites of oncogenic fusion proteins in myelodysplastic syndromes, papillary thyroid cancer, and acute promyelocytic leukemia." (PMID 33336072, 2020). "In acute promyelocytic leukaemia, myeloproliferative syndrome and papillary thyroid carcinoma, TRIM24 plays an important role as a target of chromosomal translocations to form oncogenic fusion proteins." (PMID 24409330, 2014). "Other studies showed that TRIM24 is overexpressed in acute promyelocytic leukemia and papillary thyroid carcinomas, respectively, and is a chromosomal translocation target of Braf (T18) and Ret oncogenes." (PMID 23717505, 2013). "TRIM24 is a target of chromosomal translocations to form oncogenic fusion proteins in acute promyelocytic leukaemia, papillary thyroid carcinoma and myeloproliferative syndrome." (PMID 22666376, 2012). "RET fusions (involving CCDC6, PRKAR1A, NCOA4 (ELE1), GOLGA5, TRIM24 (HTIF1), TRIM33 (RFG7), and KTN1 and ERC1 (ELKS)) are found in papillary thyroid cancers." (PMID 22928112, 2012).
head and neck squamous cell carcinoma (6 papers, 2013 to 2024). A squamous cell carcinoma that arises from any of the following anatomic sites: lip and oral cavity, nasal cavity, paranasal sinuses, pharynx, larynx, and salivary glands. "The expression levels of TRIM24 variants were examined in head and neck squamous cell carcinoma (HNSCC) samples and cell lines by real-time PCR and WB." (PMID 23717505, 2013). "The aim of this study was to investigate TRIM24 expression and its clinical significance in head and neck squamous cell carcinoma." (PMID 23717505, 2013). "However, the molecular mechanism of TRIM24 in the progression of head and neck squamous cell carcinoma (HNSCC) remains ambiguous." (PMID 29862279, 2018). "TRIM24 is often overexpressed in tumor tissues from patients with head and neck squamous cell carcinoma (HNSCC)." (PMID 39160596, 2024).
colon cancer (5 papers, 2016 to 2024). "Furthermore, ectopic expression of Trim24 induced malignant transformation in epithelial cells, while its knockdown in colon cancer cells induced apoptosis." (PMID 27773674, 2016). "Five TRIM expression was significantly upregulated (TRIM14, TRIM15, TRIM24, TRIM29, and TRIM31), and the other five TRIM genes showed decreased expression (TRIM1, TRIM3, TRIM9, TRIM22, and TRIM73) in both colon cancer (COAD) and rectal cancer (READ)." (PMID 38769340, 2024).
acute leukemia (4 papers, 2020 to 2022). A clonal (malignant) hematopoietic disorder with an acute onset, affecting the bone marrow and the peripheral blood. "While the first-generation TRIM24-specific drugs exerted poor antiproliferative effects, a selective TRIM24 degrader (dTRIM24), generated by the PROTAC strategy, inhibits cell proliferation and survival in acute leukemia." (PMID 35326630, 2022). "The TRIM24‐based PROTAC (dTRIM24) was reported to drive potent and selective degradation of TRIM24 by recruiting VHL E3, resulting in inhibition of cell proliferation in acute leukemia cells." (PMID 33482040, 2021).
brain tumor (4 papers, 2015 to 2024). "Consistent with the increased cell growth in vitro, animals with NHA/HRasV12/TRIM24 brain tumor xenografts showed significantly shortened survival." (PMID 38828688, 2024). "This treatment significantly reduced the tumor burden, as indicated by bioluminescent imaging (BLI), and markedly prolonged the overall survival of animals bearing NHA/HRasV12/TRIM24 brain tumor xenografts (P < 0.01)." (PMID 38828688, 2024). "This study provides novel insight into the TRIM24-based druggable dependencies, important for developing effective therapeutic strategies for brain tumors." (PMID 34886858, 2021). "We further injected engineered U87/EGFRvIII/TRIM24 shRNA cells transduced with an empty vector (EV), TRIM24-WT* or -F979A/N980A* into the mouse brain tumor xenograft." (PMID 29129908, 2017). "However, treatment with Dabrafenib significantly decreased the tumor burden, extended the overall survival of animals bearing NHA/HRasV12/TRIM24 brain tumor xenografts (P < 0.01), and reduced tumor Ki‐67 and ATF3 protein expression." (PMID 38828688, 2024). "To test this hypothesis, we first analyzed ATF3 protein expression in HRasV12/TRIM24 brain tumor xenografts and clinical Ep‐GBM samples." (PMID 38828688, 2024).
liver cancer (4 papers, 2014 to 2021). An epithelial or non-epithelial malignant neoplasm that arises from the liver. "TRIM24 suppressed tumorigenesis during retinoic acid receptor activation to prevent liver cancer in the murine model." (PMID 24409330, 2014).
viral infection (4 papers, 2016 to 2025). "The interaction among TRIM24, TRIM28, and TRIM33 forms a functionally significant complex that critically regulates viral infections and other cellular processes." (PMID 40421416, 2025). "In this review, we focus on Class VI TRIM proteins, including TRIM24, TRIM28, and TRIM33, highlighting the distinct functional attributes of their RING, B-BOX1, B-BOX2, COILED COIL, PHD, and BRD domains in viral infection." (PMID 40421416, 2025). "Although TRIM24 and TRIM33 SUMOylation have been shown to influence chromatin interaction and TGFβ signaling, respectively, their roles in viral infections remain underexplored." (PMID 40421416, 2025).
bladder cancer (3 papers, 2021 to 2024). "This complex regulatory interplay between TRIM28 and TRIM24 provides valuable insights into the mechanisms governing hTERT expression in bladder cancer." (PMID 39160596, 2024). "TRIM24 is overexpressed in bladder cancer and cervical cancer tissues, which drives the proliferation and invasion of cancer cells by regulating NF-κB and AKT signaling pathways." (PMID 39160596, 2024). "TRIM24 and TRIM28 have emerged as key regulators of hTERT expression in bladder cancer." (PMID 39160596, 2024). "In bladder cancer, GABPA is involved in the recruitment of two transcriptional co-regulators of telomerase expression, namely, TRIM28 (tripartite motif containing 28) and TRIM24, to the mutant TERT promoter −124A." (PMID 38033865, 2023).
endometriosis (3 papers, 2024 to 2025). The growth of functional endometrial tissue in anatomic sites outside the uterine body. "TRIM24, through NLRP3 ubiquitination and pyroptosis, causes endometriosis." (PMID 39769450, 2024).
lymph node metastasis (3 papers, 2013 to 2016). "Immunohistochemistry staining shows that the reduced TRIM24 protein is associated with lymph node metastasis (P=0.024), advance pathological TNM (pTNM) stage (P=0.046) and recurrence/metastasis (P=0.001)." (PMID 27689360, 2016). "The univariate Cox proportional analysis reveals that the TRIM24 expression (P = 0.001), smoking history (P = 0.014), tumor size (P = 0.001), lymph node metastasis (P <0.001) and pathological TNM stage (P<0.001) are significant prognostic predictors for OS and DFS." (PMID 27689360, 2016).
nasopharyngeal carcinoma (3 papers, 2023 to 2024). A carcinoma arising from the nasopharyngeal epithelium. "The interplay between miR-339-3p, KAT6A, and TRIM24 establishes an axis that plays a crucial role in prohibiting EMT in nasopharyngeal carcinoma cells." (PMID 39160596, 2024). "Notably, TRIM24 is significantly increased in nasopharyngeal carcinoma." (PMID 39160596, 2024).
Parkinson disease (3 papers, 2019 to 2024). A progressive degenerative disorder of the central nervous system characterized by loss of dopamine producing neurons in the substantia nigra and the presence of Lewy bodies in the substantia nigra and locus coeruleus. "TRIM24 is involved in transcriptional initiation and shows differential expression in individuals with Parkinson's disease." (PMID 39152475, 2024). "TRIM6 and TRIM24 play an important role in the early stage of Parkinson’s disease and can be used as early warning genes for the development of Parkinson’s disease." (PMID 36249749, 2022).